CDK4 (cyclin dependent kinase 4)
Diseases named in the same sentence as CDK4 in open-access papers (continued):
Sharing a sentence is not in itself a finding about the gene and the disease.
melanoma (continued). "Currently, clinical trials are exploring the efficacy of MEK inhibitors, either alone or in combination with pan-RAF inhibitors, CDK4/6 inhibitors, or focal adhesion kinase inhibitors, for the management of metastatic NRAS-mutant melanoma." (PMID 38891988, 2024). "After ASNS knockout, the cyclin‐dependent kinase (CDK4), cyclin‐dependent kinase (CDK6), and cyclin D1 significantly downregulated in melanoma cells, which decreased cell proliferation." (PMID 39210809, 2024). "Specifically, PRKDC amplification coupled with CDK4 amplification increased cell proliferation in S-II, whereas ROCK2 amplification elevated the increased angiogenesis and promoted melanoma metastasis in S-III." (PMID 39039072, 2024). "Anticipating the development of such resistance to a newly tested combination of CDK4/6i and MEKi, we characterised the transcriptomic responses in 3 NRAS mutant melanoma cell lines over an extended treatment duration of 33 days." (PMID 37420093, 2023). "Although previous studies have indicated a potential prognostic value of CDK4 amplification or overexpression in several cancer types, including liposarcoma and osteosarcoma, as well as acral and mucosal melanoma, it has not been proven as an independent risk factor for melanoma prognosis." (PMID 36739402, 2023). "To characterise the response of 3 NRAS mutant melanoma cell lines to a combination of MEK and CDK4/6 inhibitors, we treated the cells over 33 days and collected samples at multiple time points." (PMID 37420093, 2023). "As estimates have suggested that POT1 may be the second major high-penetrance melanoma susceptibility gene after CDKN2A, being causal of disease predisposition in 2%–4% of CDKN2A/CDK4-negative families, 14 it has been included in multiple panels for genetic testing of melanoma families." (PMID 36539277, 2023). "In melanoma, the generation of the inflammatory SASP by CDK4/6 inhibitors overcomes the immune checkpoint blockade resistance in a CD8+ T cell-dependent manner." (PMID 36612193, 2022). "Therefore, avoiding ICIs and antiangiogenic agents, while employing CDK4/6 inhibitors alone or in combination with ICIs, and targeting oxidative and lipid metabolism pathways, may be effective therapeutic strategies for melanoma patients harboring CCND1 amplification." (PMID 35844619, 2022). "In a phase Ib/II, open-label clinical trial, 102 patients with locally advanced or metastatic NRAS-mutant melanoma were treated with a MEK inhibitor (binimetinib), and a CDK4/6 inhibitor (ribociclib)." (PMID 35954441, 2022). "To interrogate the role of AKT isoforms in Cdk4/6i-induced cellular senescence, we generated isoform-specific AKT knockout human melanoma cell lines." (PMID 35158840, 2022). "In the present study, we induced senescence in two human melanoma cell lines, SK-MEL-28 and WM115, with an established cytokine cocktail of IFN-γ and TNF, the chemotherapeutic agent doxorubicin, and the CDK4/6 inhibitor palbociclib." (PMID 35563820, 2022). "A preclinical study showed that simultaneous inhibition of both MEK, which is downstream of Ras, and CDK4/6, can induce tumor regression in NRAS-mutant melanoma." (PMID 35954441, 2022). "In patient-matched healthy skin and melanoma biopsies, we found FAK was mostly inactive and nuclear localized in healthy skin, whereas melanoma lesions showed increased active cytoplasmic FAK and elevated CDK4 expression." (PMID 35525274, 2022). "The results of the survival analysis of patients with melanoma in TCGA demonstrated that the high expression of CDK2, CDK4, KIT, and VWF significantly reduced the survival rate of patients." (PMID 34582363, 2021).
melanoma (continued). "The results of this study showed that the PI3K-Akt signaling pathway and the key genes CDK2, CDK4, KIT, and VWF promoted the proliferation and metastasis of melanoma, and they were significantly related to the prognosis of patients with melanoma." (PMID 34582363, 2021). "By grouping the CDK2 and CDK4 expression levels of melanoma samples, survival analysis of patients in the high- and low-expression groups showed that the high expression of CDK2 and CDK4 significantly reduced the OS rate of patients with melanoma." (PMID 34582363, 2021). "Preclinical evidence suggests the antitumor synergistic efficacy of CDK4/6 inhibitors, with BRAF/MEK inhibitors and MEK inhibitors, in BRAF and NRAS mutant melanomas, respectively." (PMID 34831002, 2021). "KIT, PDGFRA, KDR, CDK4 and CCND1, MDM2, and TERT amplifications were frequently observed in Triple-WT melanomas." (PMID 34804979, 2021). "To gain further insight into the neoplastic potential of skin nevi, we evaluated the expression of oncogenic markers characteristic of BCC (Ptch-1, Gli-1, and Gli-2), SCC (K8, K17, and p63), and melanoma (c-kit, MAGE, and CDK4)." (PMID 33509032, 2021). "In patients with NRAS-mutant melanoma, combined MEK and CDK4/6 inhibitors have demonstrated encouraging therapeutic results." (PMID 34804979, 2021). "Using BRAF mutant melanoma cell models, we demonstrate that although CDK4/6 inhibition does not alter the metabolic phenotype following BRAF/MEK inhibition, CDK4/6 inhibition alone significantly enhances mitochondrial metabolism." (PMID 33572972, 2021). "A combination of ribociclib (a CDK4/6 inhibitor) and a MEK inhibitor (binimetinib) was evaluated in a phase 1b/2b trial in 63 patients with NRAS mutant melanomas, obtaining an ORR of 19.5% (n = 41) and a PFS of 3.7 months in the phase 2 expansion." (PMID 34831002, 2021). "Another small-molecule inhibitor, the cyclin-dependent kinase 4/6 (CDK4/6) inhibitor palbociclib, has been widely studied in the treatment of melanoma." (PMID 34001246, 2021). "To examine the function of p75NTR‐FL/CTF in melanoma, we quantified the mRNA levels of cell‐cycle effectors, including cyclin‐dependent kinase 2 (CDK2), CDK4, cyclin D1, cyclin B1 and cyclin‐dependent kinase 1 (cdc2), by quantitative RT‐PCR (qRT‐PCR)." (PMID 33247998, 2021). "The CDKN2A/CDK4/6 pathway has a role in the G1–S transition in the cell cycle, which is dysregulated in BRAF and NRAS mutant melanomas." (PMID 34831002, 2021). "Genotyping for MITF has been proposed in addition to CDKN2A/CDK4 testing for familial and multiple CM patients, and MITF-E318K carriers are encouraged to follow melanoma prevention programs and dermatologic surveillance." (PMID 34573422, 2021). "Concurrent targeting of both CDK4/6 and MEK resulted in enhanced cell death in both BRAF- and NRAS-mutant melanoma." (PMID 33806615, 2021). "Combination of CDK4/6 inhibitors with RAF/MEK inhibitors is an especially promising therapeutic approach, particularly in patients with melanoma." (PMID 33806615, 2021). "The current standard-of-care for BRAF mutant melanoma is a combination of BRAF and MEK inhibitors, and this combination with the addition of a CDK4/6 inhibitor induces sustained tumour regression in both BRAF and NRAS mutant melanoma preclinical models." (PMID 33572972, 2021). "Combined MEK and CDK4/6 inhibition is a promising therapeutic option in mutant BRAF and NRAS melanoma." (PMID 34804979, 2021). "All these results showed that CDK4 or VWF inactivation inhibits the proliferation, migration, and invasion of melanoma." (PMID 34582363, 2021). "Of note, while the effectiveness of combined MEK and CDK4/6 inhibitors has been demonstrated to some extent in both pre-clinically and clinically in NRAS codon 61 mutant melanoma, significant toxicities from this regimen have clinically been described." (PMID 33826614, 2021).
melanoma (continued). "In contrast, expression of Shh pathway components (Gli-1, Gli-2, and Ptch-1) in the nevi from P4 and P5 and melanoma markers (c-kit, MAGE, and CDK4) in the nevus from P1 was markedly increased." (PMID 33509032, 2021). "Nonsynonymous SNVs in the CDK4, MUM1 and CTNNB1 genes were among the first neoantigens isolated from melanoma by this approach." (PMID 34885172, 2021). "CDK inhibitors or CDK4 depletion, combined with MEK inhibitors, were reported to effectively suppress cell growth in melanoma cells." (PMID 32413516, 2020). "We add a further layer of complexity; both CDK4 and CDK6 are important in melanoma and their crosstalk regulates cell proliferation, viability, migration and angiogenesis." (PMID 30858922, 2019). "In this study we identify CDK4 and CDK6 as regulators of cell-proliferation, migration and tumor-angiogenesis in melanoma." (PMID 30858922, 2019). "In conclusion, our data support a role for CDK4 and CDK6 as promising therapeutic targets in human melanoma." (PMID 30858922, 2019). "This miRNA targets cyclin‐dependent kinase 4 (CDK4), cyclin D1 (CCND1) and cyclin C, and transfection of miR‐206 induces G1 arrest in multiple melanoma cell lines." (PMID 30499222, 2019). "A subgroup of melanomas that harbour combined overexpression of KIT and CDK4 has been characterized." (PMID 30858922, 2019). "To be able to assign distinct roles to CDK4 and CDK6 for melanoma formation, we performed transient siRNA as well as stable shRNA mediated knockdown of CDK4 and CDK6." (PMID 30858922, 2019). "Second, it is important to consider that the database derived observation that CDK4 is a MEK co-extinction target mimicking NRAS abrogation is, at least in part, affected by the frequent cell cycle alterations in melanoma (models) in general." (PMID 30405888, 2018). "The scenario of genetic alterations contributing to melanoma gene signature was completed by somatic CNVs, such as gene amplifications in CCND1, CDK4, KIT, MITF, and TERT as well as gene deletions in CDKN2A and PTEN." (PMID 30218391, 2018). "Finally, molecular screening of CDKN2A, p14 (specific exon-1β) and CDK4 genes, which are involved in approximately 20–40% of large, high-risk families, performed both on the proband and on the cousin affected by melanoma (III.4), did not identify any pathogenetic sequence variant." (PMID 29346284, 2018). "CDK4 was also part of the PC1, and CDK2 was part of the MITF and melanoma signature in the study of Tirosh and co-workers which is suggestive for a role of both kinases in this study." (PMID 27903987, 2017). "We used A375P melanoma cells, Hermes 3A TERT/CDK4-immortalized human melanocytes, and SGML-2 normal human melanocytes." (PMID 29262649, 2017). "On the other hand, synergistic or additive antiproliferative effects of concomitant inhibition of CDK4/6 and the MAPK pathway have been shown in melanoma cells." (PMID 29371923, 2017). "This will allow us to understand the contribution of epidermal RXRα in melanoma formation together with aberrant signaling pathways such as MAPK and CDK4 and after a single neonatal UVB exposure." (PMID 29121869, 2017). "Surprisingly, although PD0332991 is a more potent inhibitor of CDK4 (IC50=0.011 μM compared to 0.35 μM for fascaplysin), the melanoma cell lines were generally less sensitive to PD0332991 than to fascaplysin with IC50 values ranging from 0.13 to 2.29 μM." (PMID 26201960, 2015). "We also found that few well-known melanoma biomarkers like NRAS, CDK4 and CCND1 are significantly rewired in different metastatic melanoma stages, even if not differentially expressed (in the particular stage)." (PMID 26558755, 2015).
melanoma (continued). "In the case of NRAS mutant melanomas, a recent phase Ib/II clinical study with the combination of the MEK inhibitor MEK162 and a CDK4/6 inhibitor (LEE011) is being conducted (NCT01781572)." (PMID 25645078, 2015). "Next, we searched for CNAs in genes known to be affected by CNAs in melanoma (BRAF, KIT, MITF, CCND1, CDK4, PTEN, CDKN2A and AKT3)." (PMID 24399611, 2014). "XL888 was effective against NRAS mutant melanoma cells in vitro and in xenografts, most likely by decreasing protein levels of AKT, CDK4, and WEE1." (PMID 24743024, 2014). "These genes, EGFR, COL4A1, and CDK4 all shared the ‘pathways to cancer’ annotation; and EGFR and COL4A1 were shown to be involved specific cancers such as glioma, melanoma, lung cancer, bladder cancer, and pancreatic cancer." (PMID 23737970, 2013). "Thus, what more could be responsible for CYCLIN D1/CDK4 increase in melanoma cells?" (PMID 21860617, 2012). "Expression of cyclins-D1, D3 A and CDK4, as well as HMGA2 in adult and young adult-pediatric melanomas represents a central and future focus for our comparison of transgenerational melanoma specimens." (PMID 20302635, 2010). "Critically, in melanoma cells MITF is required downstream of oncogenic BRAF because it regulates expression of key cell cycle regulatory proteins such as CDK2 and CDK4." (PMID 18628967, 2008). "Nevertheless, it has recently been shown that some p16INK4a mutants failed to induced growth arrest despite retaining normal binding to CDK4, suggesting that p16INK4a mutations outside the ankyrins motifs may confer a predisposition to melanoma through a mechanism not yet identified." (PMID 14735200, 2004). "Altogether, these data suggest that the addition of the CDK2 inhibitor to CDK4/6 and CXCR1/2 inhibitors not only reduces melanoma tumor cell viability and tumor growth more effectively in BRAFWTNRASWT melanoma cells but also results in a less immunosuppressive tumor immune microenvironment." (PMID 40904502, 2025). "Although CDKN2A and CDK4 are the most commonly tested genes to date, no unique standard guidelines on which genes to include in familial melanoma genetic testing are currently available." (PMID 40869905, 2025). "Inhibitors of cyclin-dependent kinase 4 and 6 (CDK4/6) are approved for the treatment of locally advanced or metastatic breast cancer, but not for melanoma." (PMID 40904502, 2025). "However, with the development of targeted therapies (such as BRAF, MEK, CDK4/6, and C-KIT inhibitors) and immunotherapies (including anti-CTLA4 antibodies and anti-PD-1 antibodies), the systemic treatment of melanoma has been dramatically revolutionized." (PMID 40641936, 2025). "Currently, CDK4/6 inhibitors have been approved by the FDA for the treatment of advanced-stage hormone-receptor-positive, HER2-negative breast cancer and also show benefits in non-small cell lung cancer, melanoma, and head and neck squamous cell carcinoma." (PMID 40040723, 2025). "Most importantly, the inhibition of CDK4/6 was nevertheless able to reverse, in all the evaluated MPM cell lines, the ‘immune resistance programme’ that promotes T cell exclusion and resistance to immunotherapy in melanoma." (PMID 36453028, 2024). "Furthermore, research suggests a correlation between CDK4/6 activity and the subcellular localization of FAK in B16F10 melanoma cells." (PMID 38410129, 2024). "Cancer cell growth with the activation of CDK4/6 may be dependent on YAP; therefore, the inhibition of YAP may provide new therapeutic tools for insights into liver cancer and melanoma." (PMID 39791714, 2024). "Lastly, it is worth noting that MDM2 or CDK4 amplification is not exclusive to mesenchymal neoplasms; this genetic alteration has also been observed in other epithelial neoplasms or melanomas." (PMID 38275873, 2024).
melanoma (continued). "Treatment of NRAS-mutant melanoma cells with MEK and CDK4/6 inhibitors induced two divergent drug responses: fast-adapting cells characterised by increased ion transmembrane transport and an immune-like state, and slow-adapting cells with features of senescence." (PMID 38241976, 2024). "CDK4/6i treatment initially induced near-complete suppression of cell proliferation in both non-transformed and melanoma cells within 1 day." (PMID 38030655, 2023). "No cytotoxic effect was observed for the primary melanoma cell line WM3211 (VGP), with a wild type for BRAF, PTEN, N-RAS, and CDK4, and mutation at position 576 in the c-KIT gene, even for long incubation times—72 h." (PMID 37097377, 2023). "The rationale was that resistance to the MEK inhibitor by reactivating the pathway could be blunted by also blocking downstream with the CDK4/6 inhibitor, similar to combined BRAF and MEK inhibition in melanoma." (PMID 37126527, 2023). "Taken together, our results suggest that ABZ inhibits the proliferation of melanoma cells by inducing cell cycle arrest and apoptosis, and combination treatment with ABZ and a CDK4/6 inhibitor exhibits potential as a novel therapeutic strategy for the treatment of melanoma." (PMID 35383224, 2022). "Indeed, in melanoma patients, the specific CTL-intrinsic gene signature induced by CDK4/6i correlates strongly with favorable responses to anti-PD-1/L1 and anti-CTLA-4 therapy." (PMID 35444175, 2022). "To better understand how FAK could regulate CDK4/6 protein stability, we examined whether FAK-I increased ubiquitination of CDK4/6 in B16F10 melanoma cells." (PMID 35525274, 2022). "The use of both MEK and CDK4/6 inhibitors may suppress activated MAP kinase pathway and cell cycle checkpoint dysfunction in NRAS mutant melanoma, increasing antitumoral efficacy, by upregulating activity of the RTK-RAS-RAF and RTK-PI3K-AKT signaling cascade." (PMID 35053435, 2022). "Whole-exome sequencing was performed in 2 affected individuals of 5 melanoma-prone families negative for mutations in CDKN2A and CDK4, the major cutaneous melanoma risk genes." (PMID 35085295, 2022). "CDK4 expression levels may not vary in different cell lines or patients, but may be subject to the R24C mutation (which prevents the p16INK4 binding), or p16INK4 may be deleted, or cyclin D may be overexpressed, all of which lead to kinase hyperactivation in melanoma and other cancers." (PMID 35455007, 2022). "While these findings are preliminary because of the small sample size (n = 2), these data support the notion that FAK activity and cytoplasmic localization are increased within melanoma, thus enhancing nuclear FAK by FAK-Is would repress CDK4 expression and melanoma progression." (PMID 35525274, 2022). "Here, we show that CDK4/6 inhibitors increase glutamine and fatty acid-oxidation-dependent mitochondrial metabolism in melanoma cells, but they do not alter the metabolic response to MAPK inhibitors." (PMID 33572972, 2021). "Moreover, CDK4/6 are key downstream targets of MAPK signalling; therefore, the CDK4/6 pathway has emerged as a potential therapeutic target for treating melanoma patients." (PMID 33572972, 2021). "We also show that BRAF-MEKi but not CDK4/6i enhanced MHC Class I expression in melanoma cell lines in vitro." (PMID 34944961, 2021).